ZNF577 (zinc finger protein 577)
Description:
May be involved in transcriptional regulation.
Synonyms: MGC4400
Tractability: PROTAC: ubiquitination databases record sites on it.
Gene: Protein-coding gene on chromosome 19 (51,804,816 to 51,890,950, reverse strand). Ensembl gene ENSG00000161551.
Subcellular location: Nucleus
Subcellular location (Human Protein Atlas): Nucleoli; Nucleoplasm
Pathways (Reactome):
Gene expression (Transcription): Generic Transcription Pathway
Gene Ontology:
Molecular function: protein binding; DNA-binding transcription factor activity, RNA polymerase II-specific; RNA polymerase II cis-regulatory region sequence-specific DNA binding
Biological process: regulation of transcription by RNA polymerase II; regulation of DNA-templated transcription
Cellular component: nucleolus; nucleoplasm; nucleus
Genetic constraint (gnomAD): Loss-of-function variants: 14 observed, 14.71 expected, observed/expected ratio (o/e) 0.95, 90% interval 0.63 to 1.48. The upper end of that interval is the gene's LOEUF score, 1.48, which puts it in group 6 of 6, group 1 being the genes least tolerant of losing a copy. Missense variants: 551 observed, 606.89 expected, observed/expected ratio (o/e) 0.91, 90% interval 0.85 to 0.97. Synonymous variants: 202 observed, 214.17 expected, observed/expected ratio (o/e) 0.94, 90% interval 0.84 to 1.06.
Homologues: Orthologues: chimpanzee ZNF577 (98% identical), macaque ZNF577 (89% identical), pig ZNF577 (61% identical). Paralogues in human: ZNF26 (43% identical), ZNF33B (43% identical), ZNF568 (43% identical), ZNF300 (42% identical), ZNF182 (42% identical), ZNF189 (42% identical), ZNF717 (42% identical), ZNF658 (41% identical), ZNF41 (41% identical), ZNF484 (41% identical), ZFP28 (41% identical), ZNF7 (41% identical), and 164 more.
Diseases named in the same sentence as ZNF577 in open-access papers:
ZNF577 is named in the same sentence as 14 diseases in open-access papers, as found by Europe PMC text mining. Sharing a sentence is not in itself a finding about the gene and the disease. The quoted sentences say what the papers report.
Obesity (5 papers, 2020 to 2025). Accumulation of substantial excess body fat. "ZNF577 is a breast cancer risk gene in European populations, at which hypermethylation is associated with obesity and post-menopausal status in breast cancer tissue and leukocytes." (PMID 36765422, 2023). "The methylation levels of ZNF577 in breast tumors has been previously identified as a possible epigenetic mark of breast cancer associated with obesity." (PMID 32390948, 2020). "Obesity-related breast cancer has been previously associated with the methylation levels of the promoter region of ZNF577, a specific methylation pattern identified among a potential epi-signature of breast cancer in obese women." (PMID 32390948, 2020). "ZNF577, a gene involved in encoding a protein with DNA-binding transcription factor activity, has been associated with altered levels of methylation in leukocytes, particularly linked to obesity." (PMID 38397135, 2024). "As obesity is associated with aggressive PCa, ZNF577 methylation may provide a biological link between obesity and PCa progression." (PMID 34944472, 2021). "Higher levels of ZNF577 methylation in leukocytes have been associated with obesity." (PMID 34944472, 2021). "The aim of the current study was to investigate differences in methylation levels of ZNF577 depending on obesity, menopausal state and dietary pattern in blood leukocytes, a non-invasive sample." (PMID 32390948, 2020). "Accordingly, ZNF577 methylation levels in the leukocytes from women with breast cancer were higher in patients with obesity than in patients with normal-weight (p = 0.002), and in postmenopausal than in premenopausal women (p = 0.022)." (PMID 32390948, 2020). "In the context of breast cancer, an epigenetic signature of obesity-related breast cancer has been identified in breast tumor biopsies, being ZNF577 the most represented gene." (PMID 32390948, 2020). "Moreover, ZNF577 hypermethylation may serve as an epigenetic marker of obesity-related breast cancer and appears to be influenced by dietary patterns." (PMID 41373473, 2025). "In this study we evaluate the methylation levels of ZNF577 because it was among the genes of the episignature of obesity-related breast cancer previously identified and it could be a potential player in the link between obesity and breast cancer." (PMID 32390948, 2020).
breast carcinoma (4 papers, 2020 to 2025). "The results guarantee the need of performing further studies in longer longitudinal cohorts in order to elucidate the role of ZNF577 methylation in the association between breast cancer, adiposity and dietary patterns." (PMID 32390948, 2020). "In addition, recent studies have revealed an association between ZNF577 methylation levels and breast cancer, pointing to this gene as a potential biomarker of the effect of environmental factors on breast cancer." (PMID 38397135, 2024). "Independent effects of vegetables, legumes, fish and read met consumption on Methylation levels of ZNF577 in leukocytes from breast cancer women at the moment of diagnosis." (PMID 32390948, 2020). "A direct correlation was found between ZNF577 methylation levels of paired leukocytes and breast tumor tissue biopsies from 8 breast cancer women considering data from CpG1, CpG2, and mean (r = 0.62; p = 0.001)." (PMID 32390948, 2020). "In conclusion, the current work demonstrates that the methylation pattern of ZNF577 previously identified in breast cancer tissue according to the adiposity and menopausal status, can be also detected in leukocytes from the peripheral blood." (PMID 32390948, 2020). "Therefore, further studies will be needed to elucidate if the effect of dietary factors on the modulation of methylation levels of ZNF577 is also reflected in the function of this gene, and the role of this regulation on breast cancer progression." (PMID 32390948, 2020). "Therefore, ZNF577 may be a biomarker for the effect of environmental factors such as adiposity, age, and diet on breast cancer, and a suitable therapeutic target in precision nutrition and medicine." (PMID 32390948, 2020).
adenocarcinoma of the lungs (1 paper, 2018). "An example is DMR 11 (annotated to ZNF577) which was hypermethylated in our future cSCC patients and showed to be hypermethylated in SCC and adenocarcinoma of the lungs." (PMID 29946375, 2018).
breast tumor (1 paper, 2020). "In the current study, the methylation levels of ZNF577 were measured in the blood leukocytes, to evaluate if the identified methylation levels in breast tumors can be reflected in a non-invasive and easily obtained source of DNA." (PMID 32390948, 2020). "The methylation levels of ZNF577 were correlated between paired leukocytes and breast tumor biopsies (r = 0.62; p = 0.001)." (PMID 32390948, 2020). "Therefore, this study was first aimed to evaluate the capacity of circulating leukocytes to reflect the DNA methylation pattern of ZNF577 in the breast tumor tissue." (PMID 32390948, 2020).
lung carcinoma (1 paper, 2013). "Of the 12 common Significant DNA methylated genes common to Stages I and II, LY96 has been previously associated with lung cancer; ZNF577 and LVRN have been identified as methylated in lung cancer and renal carcinoma, but not in LUAD." (PMID 24369052, 2013).
lung squamous cell carcinomas (1 paper, 2017). "Frequent methylation of PTPRN2 and ZNF577 were reported in lung squamous cell carcinomas." (PMID 27926516, 2017).
myeloid malignancies (1 paper, 2018). "Such dense clusters of hypermethylation included the translocated ABL1 promoter, the promoter regions of Wilms tumor 1 (WT1), a transcription factor overexpressed in myeloid malignancies, and the promoter of the ZNF577 gene that encodes a zinc finger protein." (PMID 29575763, 2018).
prostate carcinoma (1 paper, 2025). A carcinoma that arises from epithelial cells of the prostate gland. "Of these, hsa-ZNF577 is differentially expressed between prostate cancer and paracancerous tissues, suggesting its potential as a biomarker for prostate cancer." (PMID 40391511, 2025).
prostate tumors (1 paper, 2012). "A similar fusion event between ZNF649 and ZNF577 was identified in prostate tumors." (PMID 22720068, 2012).
skin cancer (1 paper, 2021). "Another study showed higher ZNF577 methylation in T-cells from kidney transplant patients who developed de novo skin cancer than those who did not develop skin cancer, suggesting increased methylation of ZNF577 may lead to weakened immune response." (PMID 34944472, 2021).
cancer (5 papers, 2016 to 2024). A tumor composed of atypical neoplastic, often pleomorphic cells that invade other tissues. "ZNF154 and ZNF577 downregulation has been reported to be associated with several cancers." (PMID 28174608, 2017). "Several genes from the zinc finger family, including ZNF577, ZNF649, ZNF615, ZNF614, and ZNF432, are under intense investigation due to their altered methylation status in various cancer types." (PMID 36553064, 2022). "Taking ZNF577 and cg11269599 as examples, we found that the exon 1.2 and exon 1.3 of ZNF577 showed increased PSI values in five cancer types when comparing tumors to the cognate normal tissues." (PMID 31906954, 2020).
tumor (3 papers, 2013 to 2020). "For example, we found the consistent changes of AS event and cg11269599 in gene ZNF577 (zinc finger protein 577) across several tumor types." (PMID 31906954, 2020). "The ZNF577 SNPs (rs10411161, rs3848562 and rs11878583) also showed statistically significant associations in subgroups with postmenopausal women, luminal A cases, cases without family history and operable tumor stages." (PMID 23717390, 2013).
ZNF577 also shares sentences with these, for which no sentence is quoted: acute lymphoblastic leukaemia (1 paper); renal carcinoma (1).